LGALS1 (galectin 1)
Diseases named in the same sentence as LGALS1 in open-access papers (continued):
Sharing a sentence is not in itself a finding about the gene and the disease.
allergies (2 papers, 2018 to 2025). "Galectin 1 (Gal1) acts as a dual regulator of the immune system, playing protective or anti-inflammatory roles in some contexts (autoimmune diseases, allergies, atherosclerosis) while exacerbating pathological processes in others (cancer, infections, osteoarthritis)." (PMID 41009653, 2025). "Galectin-1 reduced IgE levels; however, this was only a slowing of the IgE response as, at 24 hours, galectin-1-treated mice had higher IgE levels than nontreated (allergy control) mice had." (PMID 29950926, 2018).
Alzheimer disease (2 papers, 2021 to 2025). A progressive, neurodegenerative disease characterized by loss of function and death of nerve cells in several areas of the brain leading to loss of cognitive function such as memory and language. "Genomic studies indicate that the number of galectin-1- and galectin-3-expressing microglial cells increases with age- or age-related disease (Alzheimer’s disease), reflecting an aging-associated rise in galectin concentrations within the CNS." (PMID 40429840, 2025). "A specific microglia subpopulation with increased galectin-1 expression has been identified in aging and Alzheimer’s disease (AD) cohorts." (PMID 40429840, 2025).
carcinosarcoma (2 papers, 2014 to 2021). A malignant tumor composed of a mixture of carcinomatous and sarcomatous elements. "When subdividing the US group, a significant galectin-1 up-regulation was found in leiomyosarcomas compared with myometrium (p < 0.01), carcinosarcomas (p < 0.05) and other US subtypes (p < 0.05)." (PMID 24658839, 2014). "However, galectin-1 levels in lysates of leiomyosarcomas were significantly higher compared with myometrium, carcinosarcomas and other histological subtypes of US." (PMID 24658839, 2014).
chorioamnionitis (2 papers, 2021 to 2023). A morphologic finding indicating inflammation of the fetal sac membranes. "On the other hand, considering its immunoregulatory properties, the overexpression of galectin-1 by the human chorioamniotic membrane in chorioamnionitis could represent a local protective response to counteract inflammation and establish immunological tolerance." (PMID 35008499, 2021). "Significantly increased expression of the immunoregulatory galectin-1 in the chorioamniotic membranes was also shown in cases of PPROM with chorioamnionitis compared to PPROM cases without chorioamnionitis." (PMID 35008499, 2021).
chronic gastritis (2 papers, 2013 to 2016). Inflammation of the stomach that is chronic in nature. "For LGALS1, our study showed a slightly increased relative expression only in 60% of the GA cases (mean RQ = 2.44), with an increase of 2 to 7 times, but in chronic gastritis the mean value was low (mean RQ = 0.43)." (PMID 23431236, 2013).
classic Hodgkin lymphoma (2 papers, 2014 to 2022). Classical Hodgkin lymphoma (CHL) is a B-cell lymphoma characterized histologically by the presence of large mononuclear Hodgkin cells and multinucleated Reed-Sternberg (HRS) cells. "Galectin-1 is overexpressed in patients with classical Hodgkin’s lymphoma (cHL), particularly in Reed-Sternberg (R-S) cells." (PMID 35677161, 2022). "In another study, expression of galectin-1 (Gal-1) in the tumor microenvironment (near non-tumor tissues) was associated with poor survival in classic Hodgkin lymphoma (cHL) patients." (PMID 24713112, 2014).
coronary artery disease (2 papers, 2020 to 2022). "Nevertheless, evidence for the role of galectin-1 in chronic coronary artery disease (CAD) is very limited." (PMID 33244142, 2020).
dengue (2 papers, 2014 to 2016). "Higher level of galectin-1 was found in the bacterial infection group than in other groups (37,953 pg/mL (dengue) vs. 66,963 pg/mL (bacterial infection) vs. 39,055 pg/mL (OFI) vs. 34,063 pg/mL (healthy controls))." (PMID 27240351, 2016). "Lower serum levels of galectin-1, galectin-3, and E-, L-, and P-selectin in dengue patients were detected compared to bacteria-infected patients, but not to healthy controls." (PMID 27240351, 2016). "The levels of galectin-1, galectin-3, L-selectin and P-selectin in dengue patients were different from those in patients with bacterial infection, but it was not different from those in healthy controls." (PMID 27240351, 2016). "The aim of this study was to investigate the serum concentration and potential interaction of soluble galectin-1, galectin-3, galectin-9, galectin-3 binding protein (galectin-3BP), glycoprotein 130 (gp130), and E-, L-, and P-selectin in patients with dengue fever in acute febrile phase." (PMID 27240351, 2016). "The galectin-1 level in dengue was not significantly different from galectin-1 level of healthy controls." (PMID 27240351, 2016).
Duchenne muscular dystrophy (2 papers, 2020). Duchenne muscular dystrophy (DMD) is a neuromuscular disease characterized by rapidly progressive muscle weakness and wasting due to degeneration of skeletal, smooth and cardiac muscle. "Recombinant human galectin-1 (rHsGal-1) has shown efficacy in reducing disease pathologies in murine models of Duchenne Muscular Dystrophy (DMD) through positive regulation of myogenesis and stabilization of the sarcolemma." (PMID 32881965, 2020).
follicular carcinomas (2 papers, 2015 to 2025). "Galectin-1 IHC staining in follicular carcinoma: galectin-1 was stained positively in 73.1% (19/26) of cases, while 7 cases were negative 26.9% (7/26)." (PMID 41480246, 2025). "TROP-2 expression was higher in malignant cases at 82% (papillary and follicular carcinoma) compared to galectin-1 (62%; P value, 0.0097)." (PMID 41480246, 2025). "Therefore, the present study aimed to evaluate the IHC expression of galectin-1 and TROP-2 in differentiating benign versus malignant lesions and between papillary and follicular thyroid carcinoma." (PMID 41480246, 2025).
Glucose intolerance (2 papers, 2021 to 2026). Glucose intolerance (GI) can be defined as dysglycemia that comprises both prediabetes and diabetes. "It has been reported that galectin-1 binds to the peroxisome proliferator-activated receptor-γ (PPAR-γ) pathway, promoting weight gain and glucose intolerance associated with higher-fat diets in animals." (PMID 41590667, 2026).
Infertility (2 papers, 2014 to 2025). "Maternal gal-1 promotes endometrial receptivity, and reduced LGALS1 expression is linked to unexplained infertility." (PMID 40839117, 2025). "Taking into account the fact that gal-1 has been considered an important regulator of implantation our finding could indicate this increase of galectin-1 as a possible explanation to the endometriosis-related infertility." (PMID 25473847, 2014).
infiltrating ductal breast carcinomas (2 papers, 2023 to 2024). "Based on these findings, a pooled t-test for differences in means was performed to compare mean serum galectin-1 levels between invasive ductal carcinoma and ductal carcinoma in situ, while a Welch’s t-test was performed for galectin-3 and -9." (PMID 38927753, 2024).
liver cirrhosis (2 papers, 2021 to 2023). "This cross-sectional study aims to evaluate the association of serum CLEC-2 and galectin-1 levels with PVST in patients with HBV-related liver cirrhosis." (PMID 37720512, 2023). "Our current findings support a relationship between CLEC-2/galectin-1 and PVST in patients with HBV-related liver cirrhosis." (PMID 37720512, 2023).
lung disease (2 papers, 2021 to 2023). "In particular, Galectin-1 (Gal-1) and Galectin-3 (Gal-3) act as regulators of inflammatory response in lung diseases such as COPD and idiopathic pulmonary fibrosis (IPF), making them good targets for drug design therapies." (PMID 37050230, 2023).
lung squamous cell carcinoma (2 papers, 2018 to 2025). "In the case of lung squamous cell carcinoma cells, deguelin induces apoptosis via regulating galectin-1 expression." (PMID 30405048, 2018). "Downregulate the expression of Galectin-1 in a time- and concentration-dependent manner, subsequently inhibiting the MAPK signaling pathway and inducing apoptosis in lung squamous cell carcinoma cells." (PMID 40672375, 2025).
lymphopenia (2 papers, 2021). Reduction in the number of lymphocytes. "High levels of circulating galectin-1 are directly associated with lymphopenia and radioresistance in cancer patients." (PMID 34572756, 2021).
malignant pleural mesothelioma (2 papers, 2020 to 2021). A malignant neoplasm that arises from mesothelial cells in the pleura and shows a diffuse growth pattern. "Taken together, candidate biomarkers (Galectin-1, Mesothelin, Osteopontin, shed SDC-1, VEGF, MMP-7, HGF, TIMP-1 and NRG1-β1) identified in the current study could be diagnostic biomarkers for distinguishing malignant pleural mesothelioma and metastatic adenocarcinoma from benign patients." (PMID 32731396, 2020).
medulloblastoma (2 papers, 2023). A malignant, invasive embryonal neoplasm arising from the cerebellum. "Of these seven genes (LTBP1, MAP1A, MBNL2, LGALS1, PNRC1, DAB2, and PLAAT3), only one, LGALS1, had been researched previously in relation to medulloblastoma, where it is up-regulated in MBSHH patients and activated by the SHH signalling pathway." (PMID 36831428, 2023). "The authors also identified the LGALS1 gene, which codes for galectin-1, was highly expressed in primary and secondary NES cells as well as SHH tumor samples, suggesting an important role of this gene in medulloblastoma development." (PMID 36831595, 2023).
Miscarriage (2 papers, 2024 to 2025). A pregnancy that ends at a stage in which the fetus is incapable of surviving on its own, defined as the spontaneous loss of a fetus before the 22th week of pregnancy. "Such research is limited for placental galectins and has not yet been performed for gal-1, therefore, further studies are warranted to explore the association of LGALS1, LGALS13, LGALS14, and LGALS16 polymorphism with miscarriage, PE, or IUGR." (PMID 40839117, 2025).
myeloid leukemia (2 papers, 2024). A clonal proliferation of myeloid cells and their precursors in the bone marrow, peripheral blood, and spleen. "Exploration of galectin-1 expression levels in large patient cohorts showed a clear association with fibrosis progression and significant correlation with survival in patients with myeloid leukemias." (PMID 39383242, 2024). "Myeloid leukemia cell lines consistently exhibited higher galectin-1 and 12 protein levels than lymphoid leukemia cell lines." (PMID 38184596, 2024). "Our study provides the first evidence supporting that myeloid leukemia-derived galectin-1 down-regulates CAR expression to hinder the cytotoxicity of CAR T cells." (PMID 38184596, 2024). "In addition, this study identified galectin-1 as a critical factor used by myeloid leukemia cells to induce CAR down-regulation, resulting in impaired T-cell activation." (PMID 38184596, 2024).
osteoporosis (2 papers, 2019 to 2024). A condition of reduced bone mass, with decreased cortical thickness and a decrease in the number and size of the trabeculae of cancellous bone (but normal chemical composition), resulting in increased fracture incidence. "This suggests that LGALS1 may be an important predictor of the progression of osteoporosis." (PMID 38099525, 2024).
ovarian tumor (2 papers, 2021). "Serum Galectin-1 levels were quantified in 84 newly diagnosed ovarian tumour patients and 20 healthy controls by Enzyme Linked Immuno Sorbent Assay during the course of the disease." (PMID 34556165, 2021). "In this study we investigated serum levels of Galectin-1 in patients with ovarian tumours and its efficacy as a biomarker for diagnosis and monitoring progression and response to treatment." (PMID 34556165, 2021). "The serum levels of Galectin-1(40.57± 22.2 ng/ml) in patients with newly diagnosed ovarian tumours (n=84) were significantly higher than the levels (9.19± 4.61ng/ml) (p<0.0001) in healthy controls (n=20)." (PMID 34556165, 2021). "In our study it has been reported for the first time that postmenopausal women with ovarian tumours tend to have higher levels of serum Galectin-1 than premenopausal patients." (PMID 34556165, 2021). "In this study, we have tested the clinical implications of serum Galectin-1 levels in patients with ovarian tumours." (PMID 34556165, 2021). "So in search of a better biomarker we have evaluated the levels of Galectin-1 in serum samples of patients diagnosed with ovarian tumors." (PMID 34556165, 2021). "We speculate that LGALS1 may influence the prognosis of ovarian tumors at the translation level." (PMID 33854625, 2021).
renal carcinoma (2 papers, 2021 to 2025). A carcinoma arising from the epithelium of the renal parenchyma or the renal pelvis. "LGALS1 is a potentially useful biomarker for renal cancer and is implicated in tumor progression and poor outcomes through the HIF/mTOR signaling axis in RCC patients." (PMID 34688260, 2021). "Galectin-1 inhibits the secretion process of cytotoxic cells and promotes renal cancer cells to migrate through affecting Fas–Fas ligand." (PMID 41210885, 2025).
renal fibrosis (2 papers, 2017 to 2022). A final common manifestation of a wide variety of chronic kidney diseases characterized by glomerulosclerosis and tubulointerstitial fibrosis. "Conversely, the overexpression of galectin-1 reduced type I collagen expression induced by TGF-β1 stimulation in both normoglycaemic and hyperglycaemic conditions, suggesting a protective effect of galectin-1 against renal fibrosis." (PMID 36295832, 2022).
sarcoma (2 papers, 2012 to 2014). A usually aggressive malignant neoplasm of the soft tissue or bone. "Because treatment of human sarcoma cells, SK-UT-1 and SK-LMS-1 with galectin-1 inhibited cell proliferation, low levels of galectin-1 in uterine leiomyosarcoma may contribute to the tumor growth." (PMID 22911740, 2012).
sarcopenia (2 papers, 2021 to 2024). Progressive decline in muscle mass due to aging which results in decreased functional capacity of muscles. "In muscle dystrophy, galectin-1 appears to have a protective role in sarcopenia." (PMID 38578722, 2024). "Galectin-1 is altered in muscle disease, and is increased in sarcopenia, and histochemical studies colocalize galectin-1 with leukocytes, indicating that inflammation could be an underlying mediator." (PMID 38578722, 2024). "High galectin-1 is found in sarcopenia and as a response to muscular degeneration and inflammation." (PMID 38578722, 2024).
Sepsis (2 papers, 2023 to 2025). Sepsis is defined as life-threatening organ dysfunction caused by a dysregulated host response to infection. "Finally, upon E. coli infection and intracellular LPS sensing, galectin-1 can be released through mechanisms involving non-classical inflammasome activation, gasdermin D cleavage and pyroptosis, acting as a danger-associated molecular pattern (DAMP) or alarmin during sepsis." (PMID 37582971, 2023).
serous ovarian cancer (2 papers, 2021 to 2023). "Referring to different tumor histological types, among patients with serous ovarian cancer LGALS10 overexpression predicted a better OS and LGALS1 predicted a worse OS." (PMID 33854625, 2021).
skin cutaneous melanoma (2 papers, 2021 to 2024). "Interestingly, we observed that despite the strong association of Galectin-1 (LGALS1) and PSAP with the stromal compartment, cancer cells appear to be the main source expressing these genes in skin cutaneous melanoma." (PMID 38384845, 2024).
squamous cell carcinoma (2 papers, 2014 to 2021). A carcinoma arising from squamous epithelial cells. "Accordingly, the use of Anginex (a 33 amino acid galectin-1 inhibitory peptide) combined with a suboptimal dose of radiation causes tumor regression in ovarian, mammary, and squamous cell carcinoma models." (PMID 34572756, 2021).
Trichomonas infection (2 papers, 2016 to 2022). "We used an in vitro model with siRNA galectin knockdown epithelial clones, recombinant galectins, clinical Trichomonas isolates, and mutant protozoan derivatives to dissect the function of galectin-1 and -3 in the context of Trichomonas infection." (PMID 26589797, 2016).
ulcerative colitis (2 papers, 2020 to 2021). An inflammatory bowel disease involving the mucosal surface of the large intestine and rectum. "In the present study, the well-characterized acute dextran sulfate sodium (DSS)-induced model of ulcerative colitis was used to study the function of endogenous galectin-1 during the development of intestinal inflammation." (PMID 34262567, 2021). "Due to its antiinflammatory and antioxidant activity galectin-1 may be effective in preventing and treating ulcerative colitis." (PMID 31999939, 2020). "We investigated the effect of galectin-1 on colon morphology, cell proliferation, oxidative stress, antioxidant system, and proinflammatory/antiinflammatory cytokines in a DSS-induced mouse model of ulcerative colitis." (PMID 31999939, 2020). "The effects of galectin-1 on dextran sulfate sodium (DSS)-induced ulcerative colitis in vivo is not clear." (PMID 31999939, 2020).
uterine leiomyosarcoma (2 papers, 2012 to 2014). "Quantitative real-time RT-PCR revealed that galectin-1 levels were significantly high in leiomyoma, but low in uterine leiomyosarcoma." (PMID 22911740, 2012). "We further analyzed galectin-1 expression as a candidate for the downstream effector of TrkB signaling in uterine leiomyosarcoma samples." (PMID 22911740, 2012). "In uterine leiomyosarcomas, galectin-1 levels were significantly low, consistent with earlier reports showing that galectin-1 staining was high in leiomyoma, but weak in leiomyosarcoma and myometrium." (PMID 22911740, 2012). "Future studies of galectin-1 in uterine leiomyosarcoma would provide a better understanding of BDNF-TrkB signaling mediated-cell growth." (PMID 22911740, 2012).
abortion (1 paper, 2014). the ending of pregnancy by removing a fetus or embryo before it can survive outside the uterus. "Several maternal immune-suppressive mechanisms have already been identified, including regulatory T cells, regulatory NK cells, and regulatory molecule expression such as galectin-1, PDL1, and Tim3, and failure of some of these mechanisms is associated with spontaneous abortion." (PMID 25248150, 2014).
acute peritonitis (1 paper, 2015). "The inhibitory effect of galectin-1 on leukocyte entry into tissue has been described in several in vivo inflammatory settings, including acute peritonitis, contact hypersensitivity, and paw edema models." (PMID 26216879, 2015).
adenomyosis (1 paper, 2026). The growth of endometrial tissue inside the muscular wall of the uterine corpus. "This cross-sectional study investigated galectin-1, -3, and -9 in adenomyosis." (PMID 42159239, 2026).
allergic conjunctivitis (1 paper, 2018). "The anti-inflammatory activity of galectin-1 can be used to reduce allergic conjunctivitis, an inflammation of the conjunctiva and other parts of the eye." (PMID 29950926, 2018). "In an allergic conjunctivitis model in mice, externally administered recombinantly produced galectin-1 was an inhibitor of allergic reaction." (PMID 29950926, 2018).
aortic valve stenosis (1 paper, 2019). Aortic valve stenosis (AVS) is a condition characterized by narrowing of the heart's aortic valve opening. "We detected an upregulation of complement 9 (C9), serum amyloid P-component (APCS) and transgelin as well as downregulation of heat shock protein (HSP90), protein disulfide isomerase A3 (PDIA3), annexin A2 (ANXA2) and galectin-1 in patients with aortic valve stenosis." (PMID 31856737, 2019).
autoimmune uveitis (1 paper, 2018). An autoimmune form of uveitis (disease). "Furthermore, IgE, IgG, and IgA anti-Galectin-1 (Gal-1) antibodies were increased in sera from patients with autoimmune uveitis and toxoplasmic retinochoroiditis compared to healthy controls." (PMID 29686678, 2018).
B cell lymphoma (1 paper, 2025). "In line with this, the induction of B cell lymphoma cell death by Galectin-1 and Galectin-3 also depended on the surface glycosylation of these cells." (PMID 40641998, 2025).